AR (androgen receptor)
Diseases named in the same sentence as AR in open-access papers (continued):
Sharing a sentence is not in itself a finding about the gene and the disease.
prostate carcinoma (continued). "Our observations of AR overexpression in glioblastoma and the known efficacy of AR inhibitors in prostate cancer prompted the investigation of AR antagonists’ impact on glioblastoma cells." (PMID 38203506, 2023). "As a consequence, X15695 inhibited proliferation of ER+ breast cancer and AR+ prostate cancer cells in vitro and in vivo in xenograft models." (PMID 37520743, 2023). "Here, we describe the mechanism of tumour inhibition achieved by CT7001 in prostate cancer models in vitro and in vivo and explore its efficacy as monotherapy and in combination with the widely used AR antagonist enzalutamide." (PMID 37076563, 2023). "As long as AR is present in prostate cancer, it typically remains an effective target for hormone-directed therapies." (PMID 37175938, 2023). "In this study, prompted by these emerging findings, we have investigated the effects of ALA exposure in both AR+ and AR− prostate cancer cell lines, LNCaP and DU-145, respectively." (PMID 38069431, 2023). "Proxalutamide exerted similar effects as enzalutamide, an AR antagonist prescribed for advanced prostate cancer, in decreasing AR signaling and expression of TMPRSS2 and angiotensin-converting enzyme 2 (ACE2), the SARS-CoV-2 receptor." (PMID 37459541, 2023). "In prostate cancer (PC), the AR is preferentially expressed in cells with a higher degree of differentiation, negatively regulating the maintenance of CSCs." (PMID 37894767, 2023). "In prostate cancer, it was shown to stabilise the androgen receptor (AR) transcript, leading to increased AR activity that promotes proliferation, EMT, migration and invasion." (PMID 36622663, 2023). "AR is up-regulation in the prostate cancers, and is a valuable therapeutic target in prostate cancer." (PMID 37716981, 2023). "The primary approach to prostate cancer therapy involves androgen deprivation or AR inhibition leading to an initial regression of the disease." (PMID 38201476, 2023). "The results obtained from prostate cancer cell lines and mouse models seem conflicting, and one of the major reasons is because of the differential expression of the ER-α and ER-β and the AR in these cells." (PMID 36891053, 2023). "In the castration-resistant prostate cancer (such as PC3), due to the mutation of androgen receptor, many other signaling pathways began to replace androgen receptor-related pathways to promote the progress of PCa." (PMID 37170248, 2023). "The AR signaling pathway is indispensable for normal prostate development and function but also crucial for the initiation and progression of prostate cancer." (PMID 37152995, 2023). "Prostate cancer cells are characterized by a hybrid glycolytic/oxidative phosphorylation phenotype determined by androgen receptor signaling." (PMID 36674430, 2023). "It is also known that MUC1 gene expression in prostate cancer cells is inhibited by the androgen receptor (AR)." (PMID 36980530, 2023). "In this review, we focus on androgen-targeted therapies in prostate cancer, including androgen biosynthesis inhibitors and androgen receptor antagonists." (PMID 37894395, 2023). "A novel series of androgen receptor (AR) targeting compounds for prostate cancer use a novel, exciting strategy – covalently linking Enzalutamide and EPI‐001." (PMID 36300876, 2023). "AR has been intensely studied as a driver of metastatic prostate cancer, with resistance to AR-targeting approaches resulting from various mechanisms." (PMID 37838724, 2023). "In the AR-independent prostate cancer PC-3 cells, a clear co-localization of androgen-BODIPY-conjugate- and LAMP-2-derived fluorescence signals was evident, indicating a lysosomal accumulation of these conjugates." (PMID 36835012, 2023). "Given AR alterations are selected by hormone treatment, we posited that these are relatively late events in prostate cancer evolution, emerging from established clones at the development of resistance to ADT." (PMID 37563129, 2023).
prostate carcinoma (continued). "Androgen receptor signaling plays a relevant role in the pathophysiology of prostate cancer, promoting cell growth and differentiation processes." (PMID 37894767, 2023). "This makes the effect of unsaturated fatty acids on ferroptosis especially relevant in cancers such as ER+ breast cancer or AR+ prostate cancer." (PMID 37568677, 2023). "Docetaxel was unexpectedly found to downregulate the expression of AR and PSA in AR-positive prostate cancer cells (LNCaP, CWR22Rv1, and MDA-PCa-2b)." (PMID 37444418, 2023). "The AR system remains continuously activated, leading to the inevitable development of destructively resistant prostate cancer." (PMID 38117350, 2023). "YY1 was shown by Deng and colleagues to interact directly with AR and regulate its transcriptional activity in a concentration-dependent manner in prostate cancer cells." (PMID 37686614, 2023). "Another study on differences in gut microbiota composition in prostate cancer patients showed a significant increase in Lachnospiraceae abundance in the gut of patients with oral androgen receptor axis-targeted therapy." (PMID 37764869, 2023). "Alterations in AR gene have long been noted as drivers in the progression of prostate cancer to its castration-resistant state." (PMID 37609284, 2023). "As observed for breast cancer, the presence of both ACSL4 and androgen receptor in prostate cancer cells predicts resistance to androgen deprivation therapies." (PMID 37306503, 2023). "Inhibiting the AR is widely considered as one of the most effective therapies for prostate cancer, despite its tendency to develop resistance over time." (PMID 37175108, 2023). "A recent study showed also an effect on prostate cancer based on the inhibition of the mono-ADP-ribosylation of androgen receptor (AR)." (PMID 37570820, 2023). "While GnRH agonists and antagonists exert their effects on the HPG axis, AR antagonists exert their effects on the AR of prostate cancer cells." (PMID 37273124, 2023). "The main factors influencing the growth and progression of prostate cancer are the androgen receptor and the PI3K/AKT pathway." (PMID 36835033, 2023). "Enzalutamide, a second-generation anti-androgen representation, more effectively preserves AR in the cytoplasm of prostate cancer cells." (PMID 37904122, 2023). "The AR signaling pathway is a key driver of prostate cancer progression, such that inhibiting the AR signaling pathway is of major importance in the treatment of this malignancy." (PMID 37958994, 2023). "FlnA and its proteolytic fragments directly interact with AR to regulate nuclear translocation and transcriptional activity of AR as well as androgen-dependence and metastatic phenotype of human prostate cancer." (PMID 38040692, 2023). "HDACs are established as being required for AR function in prostate cancer and HDAC inhibition can lower AR protein levels by suppressing AR mRNA transcription." (PMID 37823778, 2023). "In contrast, high-dose dihydrotestosterone abrogated the cytotoxicity of NK cells towards castration-resistant prostate cancer cells via AR/circFKBP5/miRNA-513a-5p/PDL1 signaling." (PMID 37686465, 2023). "Conversely, KLF9 was reported to suppress androgen receptor (AR) expression in prostate cancer cells, highlighting its growth inhibitory effects on androgen-dependent tumor cells." (PMID 38067370, 2023). "VNPP433-3β is a lead next generation galeterone analog that binds AR and promotes its degradation in prostate cancer cell lines and in vivo models of prostate cancer including AR-overexpressing PCa xenograft." (PMID 36831540, 2023). "As a powerful transcription factor, AR has not only been shown to play a central role in prostate cancer, but also has been demonstrated to be a plausible therapeutic target for specific breast cancer subtype and hepatocellular carcinoma (HCC)." (PMID 37092583, 2023).
prostate carcinoma (continued). "The backbone of systemic treatment for advanced prostate cancer targets the androgen receptor (AR) pathway, which also adversely impacts the cardiometabolic risk factors of the patient." (PMID 37705024, 2023). "In this line, canine prostate cancer, which is unaffected by androgen receptor aberrations, can serve as a good model." (PMID 37009802, 2023). "As an oncogenic gene in prostate cancer, ERG regulates proliferation and invasion genes by orchestrating higher-order chromatin organization, which is distinct from AR-associated chromatin connectivity." (PMID 36997534, 2023). "Twenty diterpenoids were prepared for the evaluation of their antiproliferative potency on AR-positive prostate cancer cell models (LNCaP and 22Rv1) using AR-null cell models (PC-3 and DU145) as comparisons." (PMID 37375297, 2023). "In line with this, ARLNC1 silencing leads to inhibition of AR expression and suppression of AR signaling as well as of growth of prostate cancer." (PMID 37025585, 2023). "While other genes in addition to AR are altered in prostate cancer, AR remains the primary focus of established PROTACs." (PMID 37175108, 2023). "The AR plays a critical role in prostate cancer progression by regulating genes involved in cell growth, survival, and differentiation." (PMID 37646236, 2023). "Expression of α-methyl acyl-CoA racemase (AMACR) is elevated and subsequently induces the fatty acid oxidation, an energy source in prostate cancer, independently of AR-mediated signaling." (PMID 37282627, 2023). "A study using HPE cell lines has provided an understanding of the development of prostate cancer after AR deprivation." (PMID 37282627, 2023). "AR interference — including treatment with potent, AR-signaling inhibitors (ARSIs) — is the standard therapy once prostate cancers metastasize." (PMID 37440313, 2023). "6-hydroxy-5,6-dehydrosugiol originally isolated from the stem bark of Cryptomeria japonica has been revealed to promote androgen receptor-positive LNCaP and 22RV1 prostate cancer cell apoptosis." (PMID 37375297, 2023). "At present, two critical pieces ofinformation are missing from studies on HDAC inhibitors in cancer:first, the expression profiles of various HDACs in prostate cancermodels, and second, the involvement of AR with HDACs in prostate cancer." (PMID 37191389, 2023). "Resveratrol suppressed the growth of prostate cancer via the down-regulation of androgen receptor (AR) expression in the transgenic adenocarcinoma mouse prostate model." (PMID 36674697, 2023). "The authors improve an experimental drug for castration-resistant prostate cancer by learning how the activation domain of the androgen receptor activates transcription." (PMID 38049566, 2023). "Molecular studies of AR co-activators have been widely conducted to understand prostate cancer progression." (PMID 37511059, 2023). "To identify a new AR inhibitor, we constructed a new screening system using the androgen-dependent growth of prostate cancer cell lines as a screening indicator." (PMID 37744273, 2023). "We selected the androgen-dependent growth of prostate cancer cell lines as a screening indicator because it can detect multiple steps of AR signaling." (PMID 37744273, 2023). "To benchmark the similarity of AR and its co-factors, we also compared these ALAN outputs to genes that are recurrently co-amplified with AR, even in primary prostate cancers." (PMID 37059746, 2023). "The relationship between AR and Src is well studied in prostate cancer, and AR activity is regulated by crosstalk with the Src kinase cascade, implicating activated Src as an important mediator of AR signaling." (PMID 36991029, 2023). "Another independent study reported that AR activity in 22RV1 prostate cancer cells can be suppressed by paclitaxel, as evidenced by down-regulated PSA and NKx3.1, as well as the inhibition of AR luciferase reported genes." (PMID 37444418, 2023).
prostate carcinoma (continued). "The most frequently used keywords were prostate cancer (n = 499), gene-expression (n = 291), AR (n = 263), and ER (n = 341), where ERβ (n = 219) and ERα (n = 215) also further determined the importance of ER." (PMID 37361598, 2023). "A study of prostate cancer provides evidence that PRMT5 is involved with the activation of androgen receptor (AR) transcription." (PMID 36769189, 2023). "Due to the significant role that AR and androgens play in prostate cancer initiation and development, AR expression and androgen response assays were performed." (PMID 37264224, 2023). "Studies have shown that the administration of quercetin can reduce the expression of androgen receptors (AR) on the surface of prostate cancer cells, which can be widely used in hormone therapy for this cancer." (PMID 37570691, 2023). "Enzalutamide is an AR signaling inhibitor that is currently used in different stages of prostate cancer." (PMID 37175938, 2023). "AR is a key regulator of prostate cancer and the principal target of current prostate cancer treatment collectively termed androgen deprivation therapies (ADT)." (PMID 36602710, 2023). "Metformin has been found to decrease prostate cancer cell viability and increase apoptosis through its effects on the AR signaling pathway." (PMID 37573301, 2023). "Then, the omnipotent PCSCs give rise to various sub-types of prostate cancer cells, either AR-dependent or -independent, forming PCa heterogeneity." (PMID 37108647, 2023). "This compound enhances the degradation of AR and suppresses AR-dependent transcriptional functions, exhibiting significant antitumor activity in prostate cancer models." (PMID 37705755, 2023). "Metastatic prostate cancers are initially treated with androgen deprivation therapy (ADT) because androgen and its cognate androgen receptor (AR) are critical for prostate cancer growth and progression." (PMID 36776320, 2023). "The most widely explored NHRs are estrogen (ER) and androgen receptor (AR), and their ligands are used as monotherapy or combination therapy for breast and prostate cancer." (PMID 37324449, 2023). "Prostate cancer cells such as PC-3, and numerous other cell lines with high AR levels, experience reduced AR levels in response to celastrol." (PMID 37110167, 2023). "Apalutamide is a new-generation androgen receptor (AR) antagonist that binds directly to AR and inhibits downstream AR-mediated transcription of prostate cancer-related genes." (PMID 38023146, 2023). "In conclusion, TQB3720 promotes ferroptosis in prostate cancer cells by alleviating the AR/SP1 transcriptional complex." (PMID 36744249, 2023). "In the present review, we attempt to clarify the major contribution of ncRNA-regulated mechanisms, including cancer metabolism, epigenetic modifications and abnormal AR signaling, to the occurrence of castration-resistant prostate cancer." (PMID 36674820, 2023). "In prostate cancer (PCa), androgen receptor (AR) and truncated AR (AR-7) are found in LNCaP and PC3 PCa human cell lines and can be transferred to AR-null cells." (PMID 37025182, 2023). "In the same group, they also identified that YAP acted as a context-dependent tumor suppressor in AR + prostate cancer by antagonizing TEAD-mediated AR signaling." (PMID 37211598, 2023). "In prostate cancer, androgen receptor (AR) is a key oncogenic driver, is often found amplified in the gene body and enhancer upstream of AR and is associated with aggressive progression of disease." (PMID 37234978, 2023). "In this study, we provide insight into a detailed mechanism that underlies the loss of one such negative feedback control, namely the PP2A-mediated target dephosphorylation resulting in AR-addicted prostate cancer." (PMID 37644036, 2023). "Beyond the scope of SBMA, several groups have also explored antisense-mediated knockdown of AR to treat prostate cancer, with dozens of ASOs screened and several successful candidates identified." (PMID 37628685, 2023).
prostate carcinoma (continued). "BRD9 functions as a critical regulator of androgen receptor (AR) signaling in tumorigenesis of prostate cancer." (PMID 35778964, 2023). "The dual mechanisms of action enable MSAs to suppress AR-null prostate cancer cell proliferation by cell mitosis pathway and to interfere with the AR signaling pathway in AR positive cells." (PMID 37444418, 2023). "Aberrant expression and or activity of AR is observed in most clinical cases of prostate cancer and is directly correlated to poor survival of patients." (PMID 36831540, 2023). "AR promotes DNA damage repair in prostate cancer cells; hence researchers have proposed ASIs (ENZ; BIC) in impairing DDR to radiosensitize prostate cancer cells." (PMID 36959798, 2023). "The androgen receptor (AR) plays a crucial role in regulating the cell cycle and, therefore, prostate cancer progression towards castration resistance." (PMID 36029329, 2023). "The observations of aberrant regulation of GR in neuroblastoma, ER in breast cancer, and AR in prostate cancer along with the elevated level of MDM2 in advanced stages evinced the strong correlation of MDM2 with steroid regulation." (PMID 37314603, 2023). "used AR-overexpressing LNCaP models and showed that CHD1 loss renders human prostate cancer cells more resistant to AR inhibitors in vitro and in vivo in castrated mice." (PMID 36776288, 2023). "The over-activation of a class of AR can lead to cellular dysfunction and diseases such as prostate cancer." (PMID 37998041, 2023). "Testosterone is converted to dihydrotestosterone (DHT) in the prostate, and transcriptional activity can be exerted by DHT binding to the androgen receptor, which is important in the progression of prostate cancer." (PMID 37049632, 2023). "RBN2397 inhibits the growth of prostate cancer cells in culture when cells are treated with ligands that activate the AR, or the aryl hydrocarbon receptor, and induce PARP7 expression." (PMID 37077937, 2023). "LNCaP and 22Rv1 prostate cancer cell lines were used to examine testosterone (T) import and AR activity in vitro, as they express AR and have differential expression of megalin." (PMID 36875158, 2023). "Equally important, the mechanism of action relates to the androgen receptor (AR)-signaling axis that holds the foremost impetus for the progression of castration-resistant prostate cancer, the lethal version of prostate cancer." (PMID 37111288, 2023). "Interleukin 6 (IL-6) is an anti-inflammatory myokine that has been found to activate AR-mediated gene expression via a signal transducer and activator of transcription 3 (Stat3) activator pathway in prostate carcinoma cells." (PMID 38139289, 2023). "For the prostate cancer cell lines, a similar experiment was performed using testosterone as a specific ligand for AR." (PMID 36835012, 2023). "Early stage prostate cancer is driven by AR activation and therefore androgen deprivation therapy is an effective treatment strategy at this stage." (PMID 37108576, 2023). "The cellular uptake and trafficking of the conjugates were studied in breast and prostate cancer cells expressing different combinations (or absence) of ER and AR using fluorescence microscopy." (PMID 36835012, 2023). "The visualization of cell surface PSMA and AR expression in prostate cancer cells was performed by immunocytochemistry." (PMID 37569712, 2023). "After being activated by a ligand, the AR is loaded to the dynein and then is shuttled on microtubules from the cytoplasm towards the nucleus, where the AR binds to DNA and eventually leads to prostate cancer cell proliferation and metastasis." (PMID 37444418, 2023). "AR activity expressed as a z score for each prostate cancer subtype also showed an increase in the DACH1 deletion group as compared to normal samples." (PMID 37095257, 2023). "AR plays a key role in the development and progression of prostate cancer, and genetic alterations in the AR gene have been identified in a significant proportion of PC cases." (PMID 37175108, 2023).